VWF (von Willebrand factor)
Diseases named in the same sentence as VWF in open-access papers (continued):
Sharing a sentence is not in itself a finding about the gene and the disease.
bleeding disorder (147 papers, 2007 to 2026). "Another case details a family with both deficiency of FVL and VWF, showing another example of a clotting and bleeding disorder coexisting." (PMID 41209947, 2025). "Higher plasma levels of these factors (ie, FVIII and VWF) have been associated with the risk of arterial and venous thrombosis, whereas lower levels are associated with both bleeding disorders and the reduced risk of thrombosis." (PMID 40488174, 2025). "Acquired von Willebrand syndrome (AVWS) is a rare bleeding disorder due to a deficiency of von Willebrand factor (VWF)." (PMID 40918032, 2025). "Nodal marginal zone lymphoma (NMZL) is an uncommon, mature B-cell lymphoma, rarely associated with acquired von Willebrand syndrome (AVWS), a bleeding disorder caused by von Willebrand factor (VWF) defects secondary to lymphoproliferative disorders (LPDs)." (PMID 40895701, 2025). "Among bleeding disorders, mutations were primarily found in VWF (15%), FGG (15%), F8 (12%), F7 (12%), and FGA (11%)." (PMID 40488813, 2025). "Acquired von Willebrand syndrome (AVWS) is another rare bleeding disorder characterized by deficiency and/or dysfunction of von Willebrand factor (VWF)." (PMID 41148947, 2025). "Acquired von Willebrand syndrome (AVWS) is a rare bleeding disorder characterized by either quantitative or qualitative deficiencies in von Willebrand factor (VWF)." (PMID 40918032, 2025). "VWD is caused by a defect in the amount or abnormal activity of VWF and is the most common bleeding disorder." (PMID 39845186, 2024). "Acquired von Willebrand syndrome (AvWS) is a bleeding disorder that is caused by a deficiency in the von Willebrand factor (vWF), which plays a key role in the coagulation cascade." (PMID 39219970, 2024). "Acquired von Willebrand syndrome (AVWS) is a bleeding disorder caused by alterations in the structure or function of the von Willebrand factor (VWF)." (PMID 37485275, 2023). "Decreased VWF multimers and a reduction in the ratio between VWF activity and VWF antigens are associated with bleeding disorders." (PMID 37485275, 2023). "Acquired von Willebrand syndrome (AvWS) is a rare bleeding disorder caused by dysfunction of the von Willebrand factor (vWF), leading to bleeding manifestations." (PMID 38162584, 2023). "Although VWF levels in the range of 30–50 IU/dL have been generally considered as an indication of VWD, currently this range is considered as a low normal VWF level, which is nevertheless a risk factor for developing bleeding disorders." (PMID 34575297, 2021). "It is believed that catch–slip bond transition governs the interaction of VWF with GPIbα and retains but shifts the shear stress threshold in the cases of type 2B or 2M VWF mutations that result in bleeding disorders." (PMID 34141704, 2021). "Next to vWF dysfunction or quantitative platelet defects, qualitative platelet defects, such as dysfunctional platelet membrane receptors, can be causative for bleeding disorders." (PMID 32765527, 2020). "Apart from bleeding disorders, higher plasma levels of VWF are often associated with a higher risk of cardiovascular diseases." (PMID 33015097, 2020). "The present study focused on the association between the presence of VWD, a bleeding disorder, and the SNPs (c.3445T>C; c.4975C>T; c.7603C>T) in gene code for VWF using the DNA samples of VWD patients and healthy subjects." (PMID 29423401, 2017). "VWD, due to a deficiency and/or abnormality of von Willebrand factor (VWF), represents the most frequent bleeding disorder, mostly inherited as an autosomal dominant trait." (PMID 28394285, 2017). "A newly discovered protein was recognized as the cause of hemorrhagic diathesis in these patients: the von Willebrand factor (VWF)." (PMID 28634421, 2017). "Molecular defects affecting the trafficking or exocytosis of WPBs can also give rise to alterations in circulating VWF and cause bleeding disorders." (PMID 26675235, 2016).
bleeding disorder (continued). "Mutations in VWF that result in a qualitative or quantitative defect in function cause a family of bleeding disorders collectively called von Willebrand disease." (PMID 26675235, 2016). "vWD is the most common inherited bleeding disorder and is caused by deficiency or dysfunction of vWF." (PMID 24317041, 2014). "Certain variants of VWF are known to cause a hereditary bleeding disorder." (PMID 40116934, 2025). "It should be noted that every antiplatelet therapy is highly challenging in patients with inherited bleeding disorders, such as hemophilia A and B, or Von Willebrand’s disease, the most common bleeding disorder caused by the qualitative or quantitative deficiency of the pro-VWF." (PMID 33804754, 2021). "Acquired von Willebrand syndrome (AVWS) is a bleeding disorder caused by structural or functional alterations of von Willebrand factor (VWF) commonly attributable to an underlying disease, such as hematological and autoimmune disorders and cardiovascular diseases." (PMID 28806755, 2017). "Our data unexpectedly reveal altered M. domestica VWF elongation behavior under shear forces compared to human VWF, demonstrating how basic biological research on extreme adaptations can generate new knowledge of protein function and associated bleeding disorders." (PMID 40971373, 2025). "The discovery of this and potentially other species with shear-resistant VWF may also provide a novel avenue for therapeutic exploration, where engineering similar shear-resistant VWF variants could help prevent bleeding disorders associated with left ventricular assist devices (LVAD)." (PMID 40463117, 2025). "The discovery of this and potentially other species with shear-resistant VWF may also provide a novel avenue for therapeutic exploration, where inducing similar shear-resistance in VWF may prevent bleeding disorders associated with left ventricular assist devices (LVAD)." (PMID 40971373, 2025). "It is well recognized that deficiency of VWF results in a bleeding disorder that varies in severity according to the degree of deficiency and the specific characteristics of the molecule and which may have features of both primary and secondary haemostatic defects." (PMID 28904675, 2017). "vWD is the most common inherited bleeding disorder, in which there is a defect of von Willebrand factor, a fundamental component of the hemostatic process." (PMID 41480429, 2025). "As previously stated, vWD is a common inherited bleeding disorder in which vWF function is altered, quantitatively or qualitatively." (PMID 41480429, 2025). "In contrast, VWD is characterized by a defect and/or deficiency of VWF, sometimes also accompanied by a deficiency of FVIII; VWD is the most common inherited bleeding disorder worldwide." (PMID 40723839, 2025). "Management for these patients includes extensive history taking of bleeding disorders in the family and a review of specific labs such as von Willebrand factor antigen and activity, factor VIII levels, bleeding time, and PTT." (PMID 40995259, 2025). "This bleeding disorder is characterized by reduced circulating levels of functional von Willebrand factor (VWF), which is a multimeric protein that is produced mainly by endothelial cells." (PMID 38394102, 2024). "AvWS differs from inherited vWF disorders and other bleeding disorders due to its distinct etiology and clinical presentation." (PMID 39219970, 2024). "Acquired von Willebrand syndrome (aVWS) is a rare bleeding disorder distinguished by abnormalities in the quality, function, or structure of von Willebrand factor (VWF)." (PMID 39697971, 2024). "A clinical diagnosis of vWD is made using multiple clinical criteria, including a personal history of abnormal bleeding, family history of bleeding disorders, and reduced levels of vWF." (PMID 36987359, 2023). "Patients who lack VWF exhibit a severe bleeding disorder because of defects in both platelet aggregation and blood clotting." (PMID 37485275, 2023).
bleeding disorder (continued). "Von Willebrand factor (VWF) owes its name to a Finnish physician Erik von Willebrand, who described an inherited bleeding disorder in 1924, which was later called Von Willebrand disease (VWD)." (PMID 36531725, 2022). "Type III vWD is a severe bleeding disorder inherited in a recessive manner in which there are negligible levels i.e., <5 IU/dL of plasma VWF leading to reduced factor (F) VIII levels." (PMID 35741733, 2022). "Despite the main function of regulating bleeding disorder, vWF was one of the specific surface markers of endothelial cells." (PMID 36199690, 2022). "AVWS is a rare bleeding disorder associated with similar clinical symptoms and laboratory features to VWD, where there is either a reduced activity or function of VWF, resulting in a bleeding diathesis." (PMID 35327035, 2022). "In the case of bleeding disorders related to the M-protein, it is reported that the monoclonal immunoglobulin increased the degradation of von Willebrand factor (VWF)." (PMID 34680279, 2021). "Recently, intron retention was reported in a patient with a bleeding disorder known as type I von Willebrand disease (VWD), caused by deficiency of von Willebrand factor (VWF) protein." (PMID 34948044, 2021). "Von Willebrand factor (VWF) was discovered in people living in the Aland islands suffering from a hemorrhagic disease." (PMID 34199319, 2021). "As an indirect evidence of infection-induced endothelial cell activation, increased vWF concentrations were found in 32% of A. vasorum-infected dogs suffering bleeding disorders." (PMID 34065858, 2021). "Coagulation factor deficiencies and vWF Ag and activity have been found associated with IDA in Saudi patients suffering from bleeding disorders." (PMID 33376945, 2020). "Reduced secretion of vWF results in bleeding disorders, whereas increased release of vWF following EC dysfunction is known to contribute to thrombotic disorders." (PMID 32188077, 2020). "The von Willebrand factor is a large multimeric glycoprotein found in blood plasma, and mutation of VWA causes bleeding disorders." (PMID 33552125, 2020). "The differential diagnosis for her hemostatic defect included rare congenital bleeding disorders such as undetected VWF qualitative dysfunction or undetected defects in fibrin, fibrinolysis, or platelet function." (PMID 30581553, 2018). "For her spine surgery cryoprecipitate was administered with the goal of modest replacement treatment of several exogenous coagulation factors (fibrinogen, FXIII, VWF), which were in her bleeding disorder differential diagnosis." (PMID 30581553, 2018). "Regional domain mutation of VWF, on the other hand, increases proteolytic susceptibility to ADAMTS‐13, causing a bleeding disorder, type 2A von Willebrand disease (VWD)." (PMID 29108103, 2018). "Von Willebrand Disease (VWD) is the most common human inherited bleeding disorder due to a defect of Von Willebrand Factor (VWF), which a glycoprotein crucial for platelet adhesion to the subendothelium after vascular injury." (PMID 28904675, 2017). "A handful of the candidate defects were present in genes that had previously been associated with platelet bleeding disorders, including P2RY12, VPS33B, GATA1, ANKRD26, HPS1, VWF, and LYST22." (PMID 25556537, 2015). "The snake venom cofactors described here are useful for clinical evaluation or sub-diagnosis of bleeding disorders as well as for basic investigation into the molecular mechanisms of platelet plug formation induced by VWF and platelets." (PMID 22069544, 2010). "As previously highlighted in seminal publications from Evan Sadler, mild-to-moderate reductions in plasma VWF:Ag levels should be considered as a risk factor for bleeding rather than a constitutional bleeding disorder per se." (PMID 39265913, 2024). "Another protein involved in bleeding disorders is von Willebrand factor (VWF)." (PMID 36214107, 2022). "The von Willebrand factor (vWF) was discovered in a study of inherited bleeding disorders." (PMID 33333870, 2020).
bleeding disorder (continued). "To investigate whether mucetin and stejnulxin have an effect on coagulopathy, we evaluated mice plasma recalcification time, fibrinogen concentration, von Willebrand factor (VWF) content changes and bleeding disorders after the injection." (PMID 33260875, 2020). "The most severe form of vWD is type 3, characterized by a bleeding disorder associated with a total or near-total absence of von Willebrand factor (vWF) with deficiency of plasmatic factor VIII (FVIII)." (PMID 28388959, 2017). "The following hereditary bleeding disorders were studied: severe deficiency of vWF, known as von Willebrand disease (vWD subtype III), the vWD subtypes vWD I, vWD IIa, vWD IIb and vWD 2M, deficiency of the platelet receptors GPIa, GPIb and GPIIb–IIIa, and polymorphisms of GPIa, GPIb and GPIIb–IIIa." (PMID 28031903, 2015). "The bleeding disorder may be explained by an acquired type IIA von Willebrand ‘s syndrome, which is a deficiency of high molecular weight multimers of von Willebrand factor (VWF)." (PMID 22294975, 2011). "Firstly, individuals with blood type O have lower levels of von Willebrand factor (vWF) and factor VIII compared to other blood types, which could contribute to impaired hemostasis and thus increase the risk of bleeding disorders, including conditions like APH in pregnant women with PAS." (PMID 40636918, 2025). "Taking into account that both vWF and NETs own pro-thrombotic and pro-inflammatory properties, it seems plausible to speculate that interactions between A. vasorum-induced NETs and vWF might promote the development of coagulopathies and bleeding disorders in clinical canine angiostrongylosis." (PMID 34065858, 2021). "Quantitative and functional impairment of VWF may lead to bleeding disorder." (PMID 25759835, 2014). "In individuals not on anticoagulants, the most common causes of bleeding disorders are abnormalities in level or function of von Willebrand factor (vWf) or platelets, both important components for the formation of a primary hemostatic plug at sites of vascular injury." (PMID 23724024, 2013). "The main goal of treatment in patients with bleeding disorders, including both HA and VWD, is to prevent or lessen severity of bleeding, with broad therapeutic aims to increase plasma FVIII levels in HA, or VWF, and/or FVIII in VWD." (PMID 40723839, 2025). "As part of the evaluation of a child with a suspected bleeding disorder, clinicians often request a VWD panel, which includes VWF antigen (VWF:Ag), VWF ristocetin-cofactor (VWF:RCo), and coagulation factor VIII value." (PMID 32232448, 2020). "Further investigations for bleeding disorders have been performed and an avWS was diagnosed due to the low levels of factor VIII, vWF:Ag, and vWF:RiCoF." (PMID 33391905, 2020). "Growing clinical and experimental evidence suggests the importance of the VWF–ADAMTS‐13 axis not only in hemostasis, bleeding disorders, and TTP, but also in cardiovascular disease." (PMID 29108103, 2018). "In 20% (n=12) of the patients that completed the study, a bleeding disorder was detected (1 case of type 3 VWD, 2 cases of low VWF:Ag, 1 case of probable VWD, 3 of BSS, 2 of GT, 2 of ITP, and 1 of congenital factor VII deficiency)." (PMID 24385781, 2013). "Type 3 VWD, accounting for about 5% of the VWD patients, is rare but is the most severe bleeding disorder and is characterized by the absence of circulating VWF in plasma." (PMID 37485275, 2023). "Comparison of the group diagnosed with disease (n = 14) and the group with no disease (n = 26) with a history of hemorrhagic diathesis revealed significantly different values for vWF:Ag, vWF:RCo, Col/Epi, and Col/ADP (p<0.05)." (PMID 24385752, 2013). "Comparison of the group diagnosed with disease and the group with no disease among 40 cases with a history of hemorrhagic diathesis revealed significantly different values for vWF:Ag, vWF:RCo, Col/Epi, and Col/ADP." (PMID 24385752, 2013).
bleeding disorder (continued). "In contrast with patients having a severe bleeding disorder, who usually have a clear-cut clinical and laboratory phenotype, VWD patients usually report a mild bleeding history and have a partial reduction of plasma von Willebrand factor levels." (PMID 23936622, 2013). "Treatment options for vWD include desmopressin (1-8-deamino-D-arginine vasopressin, DDAVP), a synthetic analog of vasopressin, to increase plasma factor VIII and vWF levels transiently in patients with vWD and in non-affected individuals with a bleeding disorder." (PMID 34164247, 2021). "Given that DDAVP increases the plasma levels of VWF and FVIII, it is especially effective in the treatment of patients with bleeding disorders, including VWD and people with nonsevere HA." (PMID 40290674, 2025).